MMP9 (matrix metallopeptidase 9)
Diseases named in the same sentence as MMP9 in open-access papers (continued):
Sharing a sentence is not in itself a finding about the gene and the disease.
diabetic nephropathy (continued). "A similar association has been reported by van der Zijl and colleagues between MMP-9 activity and incipient diabetic nephropathy." (PMID 33362965, 2020). "It is remarkable that, in addition to MMP-9, urinary levels of neutrophil gelatinase-associated lipocalin (NGAL) have been found to increase in patients with diabetic nephropathy." (PMID 31963569, 2020). "In studies in patients with diabetic nephropathy, the administration of vitamin E caused a reduction in the serum concentration of MMP-2, MMP-9, and TNF-α, while zinc was shown to decrease the Cd-induced expression of MMP-1 in synoviocytes." (PMID 32927885, 2020). "Compared with the normal control group, the mRNA expression of MMP-2 and MMP-9 was significantly reduced in diabetic nephropathy group." (PMID 30823598, 2019). "MMP-9 in human urine has been proposed as a marker of diabetic nephropathy and urinary tract infections (UTI)." (PMID 30564523, 2018). "We, and others, have previously demonstrated an increase in urinary MMP-9 excretion in animal models of diabetic kidney disease and proteinuric human disease." (PMID 28805677, 2017). "Matrix metalloproteinase-9 (MMP-9) is dysregulated in chronic kidney diseases including diabetic nephropathy." (PMID 28805677, 2017). "Altered expression of the gelatinases MMP-2 and MMP-9 has been associated with various glomerulopathies characterised by GBM defects, including diabetic nephropathy and Alport syndrome." (PMID 29167507, 2017). "Dysregulation of renal MMP-9 production has been reported in several different types of proteinuric kidney diseases including diabetic nephropathy." (PMID 28805677, 2017). "In this meta-analysis, variants within or near VEGFA (two variants), CCR5 (two variants), CCL2, IL-1, MMP9, EPO, IL-8, ADIPOQ and IL-10 were significantly associated with diabetic nephropathy." (PMID 25280384, 2014). "Several matrix metalloproteinases are expressed in kidney tissue, and increased concentrations of MMP-9 were found in human kidney disease, such as in acute ischemic renal disease, diabetic nephropathy, and other less common nephropathies such as lupus nephritis or postinfectious glomerulonephritis." (PMID 38136813, 2023). "Estradiol did not cause podocyte apoptosis preceding glomerulosclerosis, which was shown in the estrogen receptor (ER)-knockout mouse model, reduced albuminuria, TF progression and glomerulosclerosis by suppressing the activity of MMP-2 and MMP-9 in diabetic nephropathy." (PMID 35629404, 2022). "In addition, studies have found that DZXXI can also up-regulate the protein expression of MMP-9 in kidney tissue to achieve the purpose of treating diabetic nephropathy." (PMID 34539390, 2021). "A study carried out in MMP9-deficient mice has shown significant attenuation of albuminuria and hyperfiltration in diabetic nephropathy but without determining its effects on the glycocalyx." (PMID 32037077, 2020). "It has been proposed that urinary MMP-9 may be useful for evaluating the degree of renal injuries in patients with diabetic nephropathy, especially in the early stage." (PMID 30564523, 2018). "Therefore, it is likely that podocytes can be lost secondarily because of the invasion of PECs, which express and secret high levels of MMP-9 alone or in combination with other proteases in advanced diabetic kidney disease." (PMID 25849723, 2015). "We hypothesize that the rapid progressive nature of anti-GBM disease, which often leads to ESKD within weeks, creates a pathological context distinct from the chronic models (e.g., diabetic kidney disease, unilateral ureteral obstruction) where the pro-fibrotic role of MMP-9 is well-established." (PMID 41341833, 2025). "Therefore, MMP9 may be an important biomarker (AUC = 0.878, cut-off = −1.522) in the early stages of diabetic nephropathy and play an important role in its progression." (PMID 34790229, 2021).
diabetic nephropathy (continued). "MMP-9 expression in human podocytes and enhanced MMP-9 urinary concentrations in patients with diabetic nephropathy have also been reported." (PMID 33635529, 2021). "By examining the effect of CP in the kidney tissue of rats with Diabetic nephropathy, they indicated decreased expression of TGF-β1 and increased level of MMP-9." (PMID 34884588, 2021). "Inflammatory cytokines including TNF-α, MMP-9, and COX-2 lead the deterioration of diabetic nephropathy." (PMID 27212945, 2016). "Expression of MMP9 is enhanced in CKD including AKI and diabetic kidney disease." (PMID 39005931, 2024). "The specific mechanism of MMP-9 involved in the development of diabetic nephropathy is not fully understood." (PMID 34082748, 2021). "Some studies confirmed that the activity and abundance of MMP-2 and MMP-9 decreased in the early stage of diabetic nephropathy; therefore, renal function damage may be related to the decrease in MMP-2 and MMP-9 activities." (PMID 34819020, 2021). "In diabetic nephropathy, GAS5 expression is low and MMP9 expression is high." (PMID 34712322, 2021). "We observed increased activities of MMP and MMP-9 in diabetic rats, which are consistent with clinical studies in which, for example, the level of urinary MMP-9 is increased in patients with diabetic nephropathy, and positively correlates with the clinical stage of the disease." (PMID 33635529, 2021). "Furthermore, a microarray study of gene expression in PBMCs identified that THBS1 and COX1 genes were upregulated, while MMP9 and COX2 genes were downregulated in patients with diabetic nephropathy." (PMID 28900628, 2017). "Given these considerations, we hypothesised that high plasma levels of MMP-9 and its inhibitor TIMP-1 as well as NGAL can be related to chronic microvascular complications in individuals with type 1 diabetes, such as diabetes nephropathy and diabetes neuropathy." (PMID 33775157, 2021). "Further studies showed that GAS5 downregulated matrix metalloproteinase 9 (MMP9) expression by recruiting EZH2 to the MMP9 promoter region, while lentivirus-mediated MMP9 silencing reduced RIF and suppressed the inflammatory response in the kidneys of rats with diabetic nephropathy." (PMID 34712322, 2021). "Therefore, an identification of increased MMP-9 in activated PECs may provide an explanation of enhanced PEC proliferation and migration in diabetic kidney disease." (PMID 25849723, 2015). "In contrast, there are increasing evidences that glomerular MMP-9 protein expression and catalytic activity are enhanced in diabetic nephropathy and that the suppression of renal MMP-9 expression by genetic defect or pharmacological interventions attenuates diabetic nephropathy." (PMID 25849723, 2015). "Moreover, a study of diabetic nephropathy in a rat model indicated decreased MMP-9 expression and activity (mRNA and enzymatic activity of MMP-9: 21% and 51% respectively, p<0.05 vs. control), compatible with the increased ECM deposition associated with this disease." (PMID 23110201, 2012).
psoriasis (52 papers, 2006 to 2026). An autoimmune condition characterized by red, well-delineated plaques with silvery scales that are usually on the extensor surfaces and scalp. "Regarding psoriasis, nSMase2 activity has been implicated in the increased production of metalloproteinase-9 (MMP9) in psoriatic keratinocytes." (PMID 36837912, 2023). "Even after adjusting for sex and age, psoriasis resulted to be strongly associated with higher MMP-9 levels." (PMID 36293148, 2022). "Myr was predicted to interact with TNF, PTGS2, and MMP9—targets well documented to contribute to lesion persistence, extracellular matrix remodeling, and inflammatory amplification in psoriasis." (PMID 41471291, 2025). "Type I/III collagen degradation by MMP-9 which is upregulated in psoriasis promotes epidermal thickening." (PMID 40756258, 2025). "Network pharmacology analysis showed that 20 transdermal constituents were associated with potential therapeutic targets for psoriasis, including TNF, MMP9, TLR4, ICAM1, EGFR, and MAPK14." (PMID 41012530, 2025). "In psoriasis plaques, the levels of MMP9 and TIMP2 were greater than those in skin from healthy controls." (PMID 40756258, 2025). "A recent study showed that the skin lesion infiltrating neutrophils in psoriasis overexpressed the MMP9 gene and secreted MMP9 protein." (PMID 38166679, 2024). "Taking the intersection of these two algorithms, we finally obtained four specific gene biomarkers for psoriasis diagnosis (UGGT1\MMP9\CCNE1\ARHGEF28)." (PMID 38803495, 2024). "MMP9 was reported to be elevated in the skin lesion of both rosacea and psoriasis and acts as a key player in the pathogenesis and progression of these skin diseases." (PMID 39385245, 2024). "RT-qPCR results showed that compared to normal human epidermis, the expression of UGGT1, CCNE1, and MMP9 was significantly increased in patients with psoriasis, while ARHGEF28 expression was significantly decreased." (PMID 38803495, 2024). "Next, we found that MMP-9 was significantly elevated in the IMQ-induced psoriasis mouse model, and BZLF downregulated its expression at both the protein and RNA levels." (PMID 36950008, 2023). "Neutrophil infiltration and tortuous telangiectasia are pathological features of psoriasis, and MMP-9 can decompose a 62-amino acid peptide from IL-8 (CXCL8/CL8) to increase the chemotactic activity of neutrophils." (PMID 36950008, 2023). "Keratinocytes can also produce a variety of matrix metalloproteinases (MMPs), such as MMP2, MMP3, and MMP9, which are involved in the inflammatory responses, cell migration, and angiogenesis in psoriasis." (PMID 36555642, 2022). "Then, our data suggest a possible role of MMP-9 as a biomarker for new NMSC development in patients with psoriasis." (PMID 36293148, 2022). "Using the cyto-Hubba method, studies have recently identified 16 hub genes associated with these two diseases, in which 7 genes (MMP9, CSF2RB, IL1RN, CCL5, CD53, NCF2 and TLR2) are upregulated in both psoriasis and atherosclerosis." (PMID 35514987, 2022). "The finding that neutrophils infiltration of psoriatic skin lesions induced vascular remodeling, potentially mediated by matrix-metalloproteinase 9 (MMP-9) release, advanced the knowledge on the role of neutrophils in the pathogenesis of psoriasis." (PMID 35883760, 2022). "Chen’s data show that neutrophils and MMP-9 regulate vascular remodeling in psoriasis by regulating VEC function in the skin, which provides a powerful strategy for the treatment of psoriasis." (PMID 35693833, 2022). "Presumably, high levels of MMP9 in the psoriasis plaque lead to the rupture of the extracellular matrix, hindering its remodeling and, consequently, maintaining an inflammatory microenvironment for the rapid and inappropriate replication of keratinocytes." (PMID 34715781, 2021). "Psoriasis group has also increased protein expression of MMP9 than Control group 154.69 ± 18.94 ou/μm2 versus 109.94 ± 1.67 ou/μm2 (p < 0.0001)." (PMID 34715781, 2021).
psoriasis (continued). "Psoriasis shares a systemic production of inflammatory mediators, which are key regulators of the production of matrix metalloproteinase (MMP9) and its inhibitor TIMP1." (PMID 34715781, 2021). "MMP2 is increased in psoriasis and MMP9 is increased in atopic dermatitis, psoriasis, and urticaria." (PMID 34299145, 2021). "A significant increase was observed for MMP-9 in psoriatics and diabetics with psoriasis (p < 0.0001) with respect to diabetics and in diabetics with psoriasis (p < 0.0001) compared with psoriatics." (PMID 33834030, 2021). "The increase of MMP9 in psoriasis patients’ blood-circulating cells is another piece of evidence that this disease presents systemic characteristics." (PMID 34715781, 2021). "The increase in protein levels of MMP9 in the tissue affected by psoriasis, observed in the present study, corroborates the results described in the literature." (PMID 34715781, 2021). "In psoriasis, MMP9 also significantly upregulates the mRNA levels of ICAM-1, IL1β and CXCL1 in vascular endothelial cells (VECs), which enables VECs interaction with more leukocytes." (PMID 34122426, 2021). "It has been described in the literature that MMPs, including MMP9 levels, are higher in the serum of patients with psoriasis." (PMID 34715781, 2021). "We concluded that circ_0061012 elevated the expression of Ki67 and MMP9 to promote psoriasis progression through targeting miR-194-5p/GAB1 axis." (PMID 33393621, 2021). "Matrix metalloproteinase-2 and MMP-9 higher levels were observed in diabetics, psoriatics, and diabetics with psoriasis than in controls (p < 0.0001 for both)." (PMID 33834030, 2021). "Plasma levels of MMP-9 was significantly elevated in psoriasis patients compared with healthy individuals." (PMID 31670376, 2019). "MMP-9 is a zinc-dependent endopeptidase that contributes to extracellular matrix degradation and aberrant tissue remodeling, processes that are dysregulated in chronic inflammatory skin conditions like psoriasis and eczema." (PMID 41404493, 2025). "These previous studies clearly indicate that targeting SOD and MMP9 enzymatic activity could be an effective alternative for treating rosacea and psoriasis." (PMID 39385245, 2024). "At present, MMP-9 has been shown to play an important role in the pathogenesis of psoriasis." (PMID 36950008, 2023). "MMP-9 is one of the regulators of keratinocyte proliferation, so it’s up-regulation is related to the excessive proliferation of keratinocyte, as observed during the pathogenesis of psoriasis." (PMID 36837912, 2023). "Therefore, MMP-9 was chosen to examine the possible mechanism by which BZLF downregulates LCN2 to improve psoriasis-like skin lesions." (PMID 36950008, 2023). "Dermal pathologists have mainly studied the function of MMP-9 in chronic wounds and psoriasis." (PMID 36077255, 2022). "In addition, CXCL8, STAT1, and MMP9 were upregulated in both psoriasis and atopic dermatitis disease model samples vs. normal samples by the Western blot analyses." (PMID 35586812, 2022). "Interestingly, in our study, patients with psoriasis who developed NMSC at follow-up showed increased plasma MMP-9 compared to basal MMP-9 levels." (PMID 36293148, 2022). "We brought forth the conclusion that CXCL8, STAT1, and MMP9 may essentially implicate in disease of psoriasis and atopic dermatitis as the potential therapeutic targets." (PMID 35586812, 2022). "Patients with psoriasis who developed NMSC at follow-up showed increased plasma MMP-9 levels." (PMID 36293148, 2022). "Moreover, patients with psoriasis who developed NMSC at follow-up showed increased plasma MMP-9 levels compared to basal MMP-9 levels." (PMID 36293148, 2022). "Additionally, the same study reported that MMP-9 inhibition decreases vascular permeability and cutaneous vasodilation in an animal model of psoriasis." (PMID 36077255, 2022). "In conclusion, NGAL and MMP-9 seem to be promising serum biomarkers of psoriasis and NMSC." (PMID 36293148, 2022).
psoriasis (continued). "Studies have confirmed MMP9 is overexpressed in psoriatic neutrophils, and detected to be abundant in psoriatic skin lesions, especially adjacent to endovascular and perivascular tissues, indicating MMP9 may play a role in vascular remodeling in psoriasis." (PMID 34122426, 2021). "Significant decrease of MMP-9 and MMP-2 levels in the sera was associated with clinical improvement and with the decrease of TNF-α, VEGF, and E-selectin, angiogenic molecules already known to be implicated in clinical expression of psoriasis." (PMID 24396598, 2013). "Our findings show the existence of a direct relationship between MMP-9 and TNF-α production strongly suggesting that MMP-9 may play a key role in the skin inflammatory process in psoriasis." (PMID 17022813, 2006). "Furthermore, MMP-9 released from neutrophils in psoriasis patients could stimulate degradation of laminins." (PMID 35317170, 2022). "Concurrently, migrating neutrophils overexpress matrix metalloproteinase-9 (MMP-9), promoting psoriasis progression by inducing vascular remodeling, enhancing endothelial activation, and driving the accumulation of CD4+ T cells." (PMID 41009795, 2025). "In summary, patients with psoriasis exhibit increased expression of MMP-1, MMP-2, and MMP-9 at both the gene and protein levels, partly correlating with inflammation intensity." (PMID 41226358, 2025). "Treatment-response data further support the involvement of MMPs in psoriasis pathogenesis: in patients receiving anti-TNF-α therapy, reductions in MMP-9 levels were observed in PBMCs, serum, and skin, paralleling clinical improvement." (PMID 41226358, 2025). "We constructed the predicted PPI networks and functional modules related to psoriasis and atopic dermatitis and distinguished the key candidate target genes CXCL8, STAT1, and MMP9 in the diagnosis and therapy of similar pathogenesis." (PMID 35586812, 2022). "A series of psoriasis-related genes, such as S100A8, S100A9, KRT6A (keratin 6A), KRT6B, KRT6C, KRT16, and MMP9 (metalloproteinase 9), were also down-regulated." (PMID 35273606, 2022). "Higher MMP-9 plasma levels were also present in patients with psoriasis and NMSC than in patients with psoriasis alone." (PMID 36293148, 2022). "Many other studies have reported that the protein expression levels of PPARG, MMP9, and MYC were also strongly correlated with the incidence of psoriasis." (PMID 35265149, 2022). "In psoriasis patients, overproduction of multiple cytokines, for instance, TNF-α, IL-1, and IFN-γ, was expected to result in an increased expression of MMP-9." (PMID 35317170, 2022). "Gene interaction analyses highlighted IFNG, IL4, IL10, MMP9 and TIMP1 in IBD; IL10, IL13 and PTGS2 in psoriasis; IL8, IL10 and PTGS2 in RA." (PMID 20444268, 2010). "Indeed, in our study, patients with psoriasis showed higher plasma NGAL and MMP-9 levels than controls." (PMID 36293148, 2022). "MMP9 is regulated by tumor necrosis factor-alpha (TNF-α), which plays a central role in psoriasis." (PMID 34715781, 2021). "The significant increase in the expression of heparanase-1 (HPSE), heparanase-2 (HPSE2), syndecan-1 (SYND1), metalloproteinase-9 (MMP9), and tissue inhibitor of metalloproteinase 2 (TIMP2) in biopsies of skin affected by psoriasis showed extracellular matrix alterations in psoriasis." (PMID 34715781, 2021). "Therefore, we hypothesized that BZLF alleviated inflammation in psoriasis-like skin lesions and inhibited the proliferation of KCs, which was related to the downregulation of the LCN2/MMP-9 axis." (PMID 36950008, 2023). "However, it is important to note that the protein expression of MMP9 is also significantly higher in the non-affected tissue of patients with psoriasis compared to the control group." (PMID 34715781, 2021).